CLDN15 (claudin 15)
Description:
Forms paracellular channels: polymerizes in tight junction strands with cation- and water-selective channels through the strands, conveying epithelial permeability in a process known as paracellular tight junction permeability. In intestinal epithelium, allows for sodium and water fluxes from the peritoneal side to the lumen of the intestine to regulate nutrient absorption and intestinal morphogenesis (By similarity).
Tractability: Antibody: UniProt places it where antibodies can reach, with high confidence; UniProt predicts a signal peptide or a membrane-spanning region; its Gene Ontology location is reachable by antibodies, with medium confidence.
Gene: Protein-coding gene on chromosome 7 (101,232,092 to 101,238,820, reverse strand). Ensembl gene ENSG00000106404.
Subcellular location: Cell junction, tight junction; Cell membrane
Pathways (Reactome):
Cell-Cell communication: Tight junction interactions
Gene Ontology:
Molecular function: paracellular tight junction channel activity; identical protein binding; structural molecule activity
Biological process: paracellular transport; calcium-independent cell-cell adhesion; regulation of intestinal D-glucose absorption; regulation of intestinal lipid absorption
Cellular component: plasma membrane; tight junction; bicellular tight junction; lateral plasma membrane; membrane
Genetic constraint (gnomAD): Loss-of-function variants: 9 observed, 21.88 expected, observed/expected ratio (o/e) 0.41, 90% interval 0.25 to 0.72. The upper end of that interval is the gene's LOEUF score, 0.72, which puts it in group 2 of 6, group 1 being the genes least tolerant of losing a copy. Missense variants: 248 observed, 294.36 expected, observed/expected ratio (o/e) 0.84, 90% interval 0.76 to 0.94. Synonymous variants: 148 observed, 126.95 expected, observed/expected ratio (o/e) 1.17, 90% interval 1.02 to 1.34.
Homologues: Orthologues: chimpanzee CLDN15 (99% identical), macaque CLDN15 (97% identical), pig CLDN15 (85% identical), rabbit CLDN15 (82% identical), dog CLDN15 (82% identical), rat Cldn15 (78% identical), mouse Cldn15 (78% identical), guinea pig CLDN15 (77% identical), tropical clawed frog cldn15 (57% identical), zebrafish cldn15lb (40% identical). Paralogues in human: CLDN10 (40% identical), CLDN3 (36% identical), CLDN9 (35% identical), CLDN4 (35% identical), CLDN19 (33% identical), CLDN6 (33% identical), CLDN7 (32% identical), CLDN5 (32% identical), CLDN1 (31% identical), CLDN8 (30% identical), CLDN14 (30% identical), CLDN17 (30% identical), and 10 more.
Diseases named in the same sentence as CLDN15 in open-access papers:
CLDN15 is named in the same sentence as 36 diseases in open-access papers, as found by Europe PMC text mining. Sharing a sentence is not in itself a finding about the gene and the disease. The quoted sentences say what the papers report.
breast carcinoma (5 papers, 2019 to 2023). "In breast cancer, a low Claudin-15 expression is associated with triple-negative tumours, which are the most aggressive neoplastic group." (PMID 37761312, 2023). "Constitutional genes with increased breast cancer relapse risk were claudin 15, WDFY2, golgin A4, DOCK4 while HCG27 and PLAC8L1 were among 18 signature signs not endorsed by prognostic index score." (PMID 33106505, 2020). "CLDN15 has been shown to be a positive indicator associated with malignant pleural mesothelioma in clinical contexts, while CLDN16 is a predictor of oral squamous cell carcinoma, breast cancer, and thyroid cancer." (PMID 35281827, 2022). "Gene expression-based signatures to predict physiological process or prognosis such as the E/S.score or the CV score (CLDN15/VIM) in MPM, as well as response to treatment is becoming popular, and some of them have been evaluated in phase 3 clinical trials for breast cancer." (PMID 34261524, 2021).
colitis (5 papers, 2009 to 2023). Inflammation of the colon. "The protective effect of intestinal VDR against colitis is associated with expression of the VDR target gene Cldn15, which encodes the tight junction protein claudin-15." (PMID 36834927, 2023). "Overexpression of intestinal epithelial VDR resulted in significantly increased claudin-15 and decreased susceptibility to chemically and bacterially induced colitis." (PMID 35406694, 2022). "We confirm that claudin-15 is a direct Hnf4α gene target in the intestinal epithelial context and is down-modulated in mouse experimental colitis and inflammatory bowel disease." (PMID 19898610, 2009). "In addition, decreased Claudin-15 has been found in the inflamed region of human colonic biopsies of patients with ulcerative colitis, as well as in the colitis animal model." (PMID 37869506, 2023). "Colonic claudin-15 was reduced in VDR∆IEC mice, which were susceptible to colitis." (PMID 35406694, 2022).
malignant pleural mesothelioma (3 papers, 2021 to 2023). A malignant neoplasm that arises from mesothelial cells in the pleura and shows a diffuse growth pattern. "Recently, it was stated that the CLDN15 is a diagnostic marker for malignant pleural mesothelioma." (PMID 37799140, 2023).
mesothelioma (3 papers, 2021 to 2024). A usually malignant and aggressive neoplasm of the mesothelium which is often associated with exposure to asbestos. "We also investigated the expression of CLDN15 on non-mesothelioma tumors by using tissue microarrays of 24 primary tumors." (PMID 34131154, 2021). "have reported that claudin-15 may be valuable in subtyping mesotheliomas." (PMID 39364319, 2024). "The ability to accurately subtype mesotheliomas using markers like claudin-15 could therefore play a crucial role in predicting disease outcomes and tailoring treatment strategies to individual patient needs, enhancing the overall management of this challenging malignancy." (PMID 39364319, 2024).
malnutrition (2 papers, 2020 to 2024). Inadequate nutrition resulting from poor diet, malabsorption, or abnormal nutrient distribution. "Intestinal claudin-15 KO leads to malabsorption, and simultaneous KO of claudin-2 and claudin-15 results in severe malnutrition and death." (PMID 38712627, 2024). "Indeed, it has been shown that claudin-2 and claudin-15 double-knockout mice die as a result of malnutrition in early infancy, suggesting that claudin-2 could also be contributing to Na+-dependent nutrient absorption." (PMID 31936130, 2020).
celiac disease (1 paper, 2018). An autoimmune genetic disorder with an unknown pattern of inheritance that primarily affects the digestive tract. "Also, for claudin-15 an increased expression has been reported in celiac disease." (PMID 30728783, 2018).
colorectal cancer (1 paper, 2022). A primary or metastatic malignant neoplasm that affects the colon or rectum. "Our findings revealed that the mRNA expression levels of CLDN1, CLDN2, CLDN12, and CLDN14 were upregulated in colorectal cancer tissues relative to normal tissues in the Oncomine database, whereas CLDN3, CLDN5, CLDN7, CLDN8, CLDN11, CLDN15, and CLDN23 were downregulated, as previously reported." (PMID 35281827, 2022).
cutaneous melanoma (1 paper, 2015). A primary melanoma arising from atypical melanocytes in the skin. "Thus hypermethylation of distinct Claudins were frequently reported in human cancers and it will be interesting to analyze the methylation of several Claudin family members (e.g., CLDN1 and CLDN15) in cutaneous melanoma." (PMID 26198249, 2015).
cyst (1 paper, 2020). A sac-like closed membranous structure that may be empty or contain fluid or amorphous material. "Cldn15 was detected in both the cyst and tubular structures but expressed at a relatively higher level in the tubular structures." (PMID 32206088, 2020). "In terms of bile duct organization, the tubular also maintained better bile duct organization than in the cyst as determined by higher Cldn15 expression." (PMID 32206088, 2020).
Epithelioid mesothelioma (1 paper, 2025). "Epithelioid mesothelioma is known to express elevated levels of Claudin-15 and other epithelial markers, whereas non-epithelioid tumors tend to exhibit mesenchymal features such as Vimentin expression." (PMID 41463232, 2025).
glioma (1 paper, 2025). A benign or malignant brain and spinal cord tumor that arises from glial cells (astrocytes, oligodendrocytes, ependymal cells). "Given the crucial roles of CLDN12 and CLDN15 in maintaining tight junctions and barrier function, their CNV‐driven expression changes might significantly impact glioma progression through altered cell–cell adhesion and blood–brain barrier integrity." (PMID 41425851, 2025).
Hyperglycemia (1 paper, 2020). An increased concentration of glucose in the blood. "Taken together, these data suggest that SELL, ITGA4, ARHGAP35, CLDN15 may be closely associated with β-cell autoimmunity in patients with LADA, and the increase of other genes in LADA may only reflect the hyperglycemia status." (PMID 33391182, 2020).
lung adenocarcinoma (1 paper, 2021). A carcinoma that arises from the lung and is characterized by the presence of malignant glandular epithelial cells. "Since it is clinically important to differentiate lung adenocarcinomas from MPMs, we immunostained lung adenocarcinoma sections for CLDN15 and other positive markers." (PMID 34131154, 2021). "In 50 lung adenocarcinoma sections, four cases were positive for CLDN15 and the specificity (92%) was comparable with other markers (90–100%)." (PMID 34131154, 2021). "An important cancer to differentiate from MPM is lung adenocarcinoma; the false-positive rate of CLDN15 in lung adenocarcinoma is 8%, which is comparable with other MPM-positive markers, such as calretinin (10%)." (PMID 34131154, 2021). "Furthermore, CLDN15 was negative in most tumors examined, including lung adenocarcinomas." (PMID 34131154, 2021).
lung squamous cell carcinomas (1 paper, 2021). "In lung squamous cell carcinomas, which are another cancer to be distinguished from MPMs, we found no false positives for CLDN15 (n = 11)." (PMID 34131154, 2021).
malignant mesothelioma (1 paper, 2024). A malignant neoplasm of the pleura or peritoneum, arising from mesothelial cells. "Claudin-15 (CLDN15) has been reported to be expressed in malignant mesothelioma." (PMID 38540693, 2024).
mesothelial tumors (1 paper, 2021). "Notably, CLDN15 was rarely detected in 24 non-mesothelial tumors in the tissue microarray (12/327 cases)." (PMID 34131154, 2021).
osteosarcoma (1 paper, 2023). A usually aggressive malignant bone-forming mesenchymal neoplasm, predominantly affecting adolescents and young adults. "Importantly, NMD is particularly pronounced in osteosarcomas, and the absence of adequate cell-to-cell adhesions (e.g., CLDN1, CLDN15) and a potent host immune response, makes vitamin D3 a likely candidate for combined immunotherapy." (PMID 37228489, 2023).
ovarian carcinoma (1 paper, 2021). A malignant neoplasm originating from the surface ovarian epithelium. "In addition, high expression of CLDN10 and CLDN15 were predictive of a good prognosis in ovarian cancer patients." (PMID 34249076, 2021). "Among them, CLDN3, CLDN4, CLDN6, CLDN10, CLDN15, and CLDN16 were significantly correlated with overall survival in patients with ovarian cancer." (PMID 34249076, 2021). "Furthermore, three genes showed low expression in the ovarian cancer samples compared with normal tissue samples and included CLDN5, CLDN11, and CLDN15." (PMID 34249076, 2021).
Pleural effusion (1 paper, 2023). The presence of an excessive amount of fluid in the pleural cavity. "In this work, we confirmed the deregulation of CFB, MSLN and CLDN15 on pleural effusions from epithelioid and biphasic PM." (PMID 38067238, 2023).
sarcomatoid mesothelioma (1 paper, 2023). A diffuse malignant mesothelioma arising from the pleura and less often the peritoneum. "This could represent an additional step towards epithelial-to-mesenchymal transition and could explain the low Claudin-15 expression in sarcomatoid mesothelioma." (PMID 37761312, 2023).
type 2 diabetes (1 paper, 2020). "We further measured and compared the gene expression of CXCR1, SELL, ITGA4, ITGAM, NCF4, ARHGAP3, and CLDN15 in neutrophils from 5 type 2 diabetes patients within 1 year from diagnosis and 5 age- and sex-matched healthy control subjects." (PMID 33391182, 2020).
uterine cancer (1 paper, 2024). Primary or metastatic malignant neoplasm involving the uterine corpus and/or the cervix. "VWCE and CLDN15 have previously been associated with various neoplasms; however, their role in uterine cancers remains largely undescribed." (PMID 38540371, 2024).
tumor (6 papers, 2019 to 2024). "Levels of mRNA encoding claudin 15 (CLDN15) and vimentin (VIM) were determined using RT‐qPCR on 483 cases to estimate the relative proportions of epithelial‐like and mesenchymal‐like components in each tumor." (PMID 32944962, 2021). "We examined the expression of CLDN15 in MPM tissue samples by immunohistochemistry using the 2C11 clone, and found that the membrane, as well as the cytoplasm, of only the tumor cells are positive for CLDN15." (PMID 34131154, 2021). "No significant results were observed between the tumour grade and immunohistochemical expression of Claudin-15 and CFB." (PMID 37761312, 2023). "However, claudin-15 functions primarily as a pore forming protein, and HEPACAM2 is a purported tumor suppressor, thus reductions to their abundance likely would not increase epithelial permeability." (PMID 34147126, 2021).
cancer (4 papers, 2014 to 2023). A tumor composed of atypical neoplastic, often pleomorphic cells that invade other tissues. "Moreover, hypermethylation of CLDN6, CLND7 and CLDN15 have also been observed in different cancer entities." (PMID 26198249, 2015). "Since CLDN15 is expressed on the cell surfaces of MPM cells specifically, it would be a potential target for anti-cancer drugs." (PMID 34131154, 2021).
infection (2 papers, 2017 to 2025). The state of being infected such as from the introduction of a foreign agent such as serum, vaccine, antigenic substance or organism. "Notably, in EcN + C. jejuni, the expression of the CLDN15 encoding gene was up-regulated in comparison to infection with C. jejuni." (PMID 28878749, 2017). "At the peak of the infection, genes related to antimicrobial defense and barrier function, including Reg3a, Reg3g, Defb37, Defb40, Claudin-8, and Claudin-15, also showed altered expression, suggesting weakened antimicrobial protection and impaired tight junction integrity." (PMID 40630939, 2025).
brain diseases (1 paper, 2025). "The results provide insights into Cldn15 structure and function and validate a structural model of BBB TJs useful for studying barrier impairment in brain diseases and for developing therapeutic approaches." (PMID 40862374, 2025).
CLDN15 also shares sentences with these, for which no sentence is quoted: asthma (1 paper); colon adenocarcinoma (1); colon cancer (1); congenital heart malformation (1); hypoplastic left heart syndrome (1); inflammatory bowel disease (1); oral squamous cell carcinoma (1); thyroid cancer (1); ulcerative colitis (1); ventricular septal defect (1).